RNU1-44P (RNA, U1 small nuclear 44, pseudogene)
Gene: Small nuclear RNA gene on chromosome 4 (146,580,048 to 146,580,210, forward strand). Ensembl gene ENSG00000207182.
Homologues: Orthologues: chimpanzee U1 (97% identical), macaque U1 (90% identical). Paralogues in human: RNU1-1 (88% identical), RNU1-2 (88% identical), RNU1-27P (88% identical), RNU1-28P (88% identical), RNU1-3 (88% identical), RNU1-4 (88% identical), RNVU1-18 (88% identical), RNVU1-29 (88% identical), RNVU1-31 (88% identical), U1 (88% identical), RNVU1-28 (88% identical), RNVU1-7 (88% identical), and 134 more.